SULT1A1 (sulfotransferase family 1A member 1)
Diseases named in the same sentence as SULT1A1 in open-access papers (continued):
Sharing a sentence is not in itself a finding about the gene and the disease.
Obesity (8 papers, 2009 to 2024). Accumulation of substantial excess body fat. "Multiple studies reported an association between SULT1A1 and obesity-related traits including body fat percentage and body mass index (BMI)." (PMID 39457450, 2024). "In an animal model we demonstrate that full body Sult1a1 KO mice have a tendency for a lean phenotype and a slight resistance to diet induced obesity." (PMID 39703864, 2024). "The Chr16p11 gene set consists of 212 genes, some of which are associated with obesity, including SH2B1, APOBR, SULT1A1, SULT1A2, and TUFM." (PMID 29854750, 2018). "The regulation of SULT1A1 expression in diet induced obesity (DIO) rats in adipose tissue and liver was dependent on the dietary fat content." (PMID 25955518, 2015). "In order to fine map the chromosomal region chr16p11.2 for further obesity associated variants, we screened the coding regions of APOBR, SULT1A1, SULT1A2, and TUFM for variants in 95 extremely obese children and adolescents." (PMID 25955518, 2015). "Two other miR-125a target genes of interest in the context of T2D and obesity are Ppap2c and Sult1a1, both of which were significantly down-regulated in adipose tissue from the GK rat." (PMID 19689793, 2009). "Association of a non-synonymous SNP (rs141581853: SULT1A1 p.Arg213His) with obesity but not hypertension had been described." (PMID 25955518, 2015).
breast tumor (7 papers, 2005 to 2024). "In the present study we focused on SULT1A1 because this gene is polymorphic with common and well-described functionally significant alleles and is the estrogen-sulfating gene most highly expressed in breast tumors." (PMID 16280036, 2005). "Because estrogen exposure is a known factor in the etiology of breast tumors, and because the SULT1A1*2 allele is a low-activity allele with a high population frequency, we hypothesized that this allele might represent an important modifier of breast tumor characteristics." (PMID 16280036, 2005). "Expression in breast tumors has been documented, but the transcriptional regulation of SULT1A1 in human breast tissue is poorly understood." (PMID 24393253, 2014). "Furthermore, CNVs involving the SULT1A1 gene locus had an expression dosage effect in breast tumours." (PMID 36203093, 2022). "Based on the evidence that the level of SULT1A1 enzyme activity is correlated with CNV, our data suggest that in male breast tumors SULT1A1 activity may be decreased." (PMID 23711090, 2013). "SULT1A1 has therefore been hypothesized to be important in the sulfation of estrogens within breast tumors." (PMID 16280036, 2005). "Furthermore, because a common competing metabolic pathway for SULT1A1-mediated sulfation of estrogens is UGT1A1-mediated glucuronidation of E2, we also hypothesized that UGT1A1 alleles might represent modifiers of breast tumor characteristics." (PMID 16280036, 2005). "SULT1A1, and to a lesser extent SULT2A1, appear to be the isoforms responsible for estrogen and catecholestrogen sulfation in breast tumors." (PMID 16280036, 2005). "In breast tumor tissue, steroid sulfation is catalyzed by SULT1E1, SULT1A1, and SULT2A1." (PMID 30042681, 2018). "Based on the evidence that the level of SULT1A1 enzyme activity is correlated with CNV 2, our data suggest that in male breast tumours SULT1A1 activity may be decreased." (PMID 23711090, 2013). "Furthermore, SULT1A1 expression is related to disease state, with little to no expression in normal breast epithelia but plentiful protein expression in most breast tumors." (PMID 24393253, 2014).
gastric cancer (4 papers, 2007 to 2021). A primary or metastatic malignant neoplasm involving the stomach. "pointed out the increased gastric cancer risk in smokers with Sulfotransferase Family 1A Member 1 (SULT1A1) gene and drinkers with CYRS2070803E1 gene (*5A allele or *6 allele)." (PMID 34532288, 2021). "There are reports of SULT1A1*2 association with increased risk for oesophageal cancers as well as gastric cancer in individuals who consume alcohol and smoke tobacco." (PMID 18854828, 2008). "We also reported that individuals carriers of the SULT1A1 variant allele, who have limited detoxification capability of xeniobiotics through sulfonate conjugation, have an additional risk of gastric cancer if smokers." (PMID 17996038, 2007). "From the gene-environment interaction analysis, we showed effect modification of the association between SULT1A1 and gastric cancer by tobacco smoking, and CYP2E1 (*5A or *6 alleles) by alcohol drinking." (PMID 17996038, 2007). "We recently showed, for the first time, that SULT1A1 Arg213His polymorphism might affect the risk of gastric cancer, while contradictory results concerning several SNPs in metabolic genes have been reported." (PMID 17996038, 2007). "Gastric cancer risk was found to be associated with the inheritance of GSTT1 null genotype (OR = 2.10, 95%CI: 1.27–3.44) and the SULT1A1 His/His genotype (OR = 2.46, 95%CI: 1.03–5.90)." (PMID 17996038, 2007). "GSTT1, SULT1A1 and NAT2 polymorphisms appear to modulate individual's susceptibility to gastric cancer in this Italian population, particularly when more than one unfavourable genotype is present, or when combined with cigarette smoke." (PMID 17996038, 2007). "This study suggests that in this Italian population, GSTT1, SULT1A1 and NAT2 polymorphisms may modulate an individual's susceptibility to gastric cancer, particularly when more than one unfavourable genotype is present and in combination with cigarette smoke." (PMID 17996038, 2007).
colitis (3 papers, 2019 to 2024). Inflammation of the colon. "Sulfotransferase family 1A member 1 (Sult1a1), a protein involved in small-molecule metabolism and previously found to be down-regulated in DSS colitis, was down-regulated in both prepathologic and inflamed states." (PMID 38199279, 2024).
endometriosis (3 papers, 2019 to 2022). The growth of functional endometrial tissue in anatomic sites outside the uterine body. "Endometriosis is widely known as an inflammatory condition and serum concentrations of the inflammatory proteins Axis inhibition protein 1 (AXIN1), Sulfotransferase Family 1A Member 1 (ST1A1) and C-X-C Motif Chemokine Ligand 9 (CXCL9) have been found to be altered in women with endometriosis." (PMID 35659226, 2022).
hepatocellular carcinoma (3 papers, 2011 to 2018). A malignant tumor that arises from hepatocytes. "Patients with liver cirrhosis who had higher SULT1A1 activity had a higher risk of developing hepatocellular carcinoma than did such patients with normal SULT1A1 activity." (PMID 25514600, 2015).
leukemia (3 papers, 2015 to 2017). A malignant (clonal) hematologic disorder, involving hematopoietic stem cells and characterized by the presence of primitive or atypical myeloid or lymphoid cells in the bone marrow and the blood. "We previously reported that leukemia cells expressing SULT1A1, mostly AML cells, are susceptible to NSC-743380 treatment." (PMID 29254232, 2017). "The SULT1A1 protein levels in cell lysates from 18 leukemia cell lines reliably predicted the susceptibility of the cell lines to NSC-743380." (PMID 25514600, 2015). "Third, this report is the first to evaluate the association between genetic variability in SULT1A1 and susceptibility to childhood leukemia." (PMID 25992585, 2015). "The Western blot analysis showed that SULT1A1 was expressed in four of the leukemia lines: U937, M-07e, MV4-11, and THP-1." (PMID 25514600, 2015). "Moreover, we found that a subset of leukemia cell lines, mostly AML cells, express SULT1A1 and are highly sensitive to NSC-743380." (PMID 29254232, 2017). "We then performed the cell viability assay on six leukemia cell lines, including the four lines that expressed SULT1A1 and two cell lines (HL-60 and OCI/AML3) that did not." (PMID 25514600, 2015). "To test whether expression of SULT1A1 in other cancer cells can be used to predict responses to NSC-743380, we used Western blot analysis to determine SULT1A1 expression in cell lysates from 18 leukemia cell lines." (PMID 25514600, 2015).
oesophageal cancer (3 papers, 2007 to 2009). "The gene SULT1A1 is suspected to play a role in oesophageal cancer (OC)." (PMID 19238204, 2009).
pulmonary edema (3 papers, 2015 to 2024). Accumulation of fluid in the lung tissues causing disturbance of the gas exchange that may lead to respiratory failure. "For the first time, we also report the possible consideration of SULT1A1, as a biomarker for the diagnosis of high altitude pulmonary edema (HAPE)." (PMID 26022216, 2015).
ulcerative colitis (3 papers, 2021 to 2024). An inflammatory bowel disease involving the mucosal surface of the large intestine and rectum. "TNFRSF6B and SULT1A1 colocalised with inflammatory bowel disease, and TNFRSF6B also separately colocalised with its two main forms: Crohn’s disease and ulcerative colitis." (PMID 38565889, 2024). "SULT1A1 has been reported to be upregulated in sera of ulcerative colitis patients, while no studies on the role of SULT1A1 in arthritis have been reported." (PMID 34963488, 2021).
acute myeloid leukemia (2 papers, 2015 to 2017). Acute myeloid leukemia (AML) is a group of neoplasms arising from precursor cells committed to the myeloid cell-line differentiation. "SULT1A1 (c.638G>A) was associated to infant acute lymphoblastic leukemia and acute myeloid leukemia (AML) risk in males (additive model: aOR = 0.52; 95% CI: 0.29–0.95, p = 0.03; dominant model: aOR = 2.18; 95% CI: 1.17–4.05, p = 0.01, respectively)." (PMID 25992585, 2015). "Our recent study showed that acute myeloid leukemia (AML) cells expressing SULT1A1 are highly sensitive to NSC-743380, a small molecule that inhibits STAT3 activity and induces SULT1A1-dependent apoptosis of various cancer cell lines." (PMID 29254232, 2017).
adenoma (2 papers, 2015 to 2018). A neoplasm arising from the epithelium. "A set of transcripts (18 genes including MAL, SFRP1, SULT1A1, PRIMA1, PTGDR) showed decreasing expression (p < 0.01) in the biopsy samples along the adenoma-carcinoma sequence." (PMID 26482433, 2015).
Arthritis (2 papers, 2021 to 2025). Inflammation of a joint. "SULT1A1 is a cytosolic sulfotransferase with known impact on drug metabolism but unexplored in arthritis." (PMID 41013715, 2025).
bladder cancer (2 papers, 2015 to 2017). "Additionally, some studies provide epidemiologic evidence of a reduced bladder cancer risk in individuals with the SULT1A1 His213 allele genotypes which have been linked with an increased risk for cancer." (PMID 28178690, 2017).
endometrial cancer (2 papers, 2016 to 2021). Primary or metastatic malignant neoplasm involving the endometrium (mucous membrane that lines the endometrial cavity). "In another study, women bearing benign and malignant gynecological tumors were found to have a higher frequency of the common allele of SULT1A1, suggesting that there was an increase in endometrial cancer risk with greater SULT1A1 activity." (PMID 27322429, 2016). "However, other studies have found either no or negative correlation between SULT1A1*2 and endometrial cancer risks." (PMID 27322429, 2016).
esophageal squamous cell carcinoma (2 papers, 2009 to 2023). Esophageal squamous cell carcinoma (ESCC) is a type of esophageal carcinoma (EC) that can affect any part of the esophagus, but is usually located in the upper or middle third. "The second example is to study the interaction between the gene SULT1A1 and smoking/alcohol consumption for squamous cell carcinoma of the oesophagus." (PMID 19238204, 2009).
Hypertension (2 papers, 2016 to 2019). The presence of chronic increased pressure in the systemic arterial system. "Altogether, we found nine genes (Cst3, Cyp11b2, Ephx2, Fn1, Igfbp2, P2rx4, Prkcd, RT1-Ba, and Sult1a1) annotated in the RGD as associated with hypertension in this group." (PMID 26822062, 2016). "The annotation of DEGs in RGD (Rat Genome Database) revealed 18 genes associated with hypertension, and according to DAVID, four additional DEGs (Acta2, Hba2, P2rx4, and Sult1a1) were defined as related to regulation of BP." (PMID 32039698, 2019).
inflammatory bowel disease (2 papers, 2016 to 2024). A spectrum of small and large bowel inflammatory diseases of unknown etiology. "Moreover, SULT1A1 variation has been linked to a number of diseases such as cancer, heart disease, and inflammatory bowel disease." (PMID 26906565, 2016).
injury (2 papers, 2021 to 2024). Damage inflicted on the body as the direct or indirect result of an external force, with or without disruption of structural continuity. "We found that the four core genes (Tsc22d3, Itga6, Ermn, Sult1a1) were associated with immune system diseases, drug-related side effects and adverse reactions, chemical and drug-induced liver injury, neurological disorders, heart failure, mental disorders, and neural tube defects." (PMID 38843390, 2024). "Taken together, these findings suggest the involvement of SULT1A1 and IS in the progression or deterioration of cisplatin-induced kidney injury via the cisplatin/IS/AhR/ROS axis." (PMID 33578912, 2021).
male breast carcinoma (2 papers, 2013 to 2021). A malignant neoplasm involving the male breast. "Sulfotransferase 1A1 (SULT1A1) is a drug and hormone metabolizing enzyme involved in the metabolism of a variety of endogenous and exogenous potential breast carcinogens, the absence of which can lead to the development of male breast cancer." (PMID 34398900, 2021).
migraine (2 papers, 2014 to 2022). "SULT1A1 inhibition as a common mechanism by which medication overuse and migraine triggers modulate migraine susceptibility, possibly can help us gain insight into mechanisms relevant to migraine pathophysiology." (PMID 35282834, 2022). "SULT1A1 inhibition could be one of the underlying mechanisms of this clinical deterioration that is seen commonly in migraine patients with medication overuse." (PMID 35282834, 2022). "The relationship between dopamine levels and SULT1A1 inhibition, CSD and migraine susceptibility remains to be established." (PMID 35282834, 2022). "SULT1A1 inhibition may be the common mechanism by which food triggers and NSAIDs modulate CSD and migraine susceptibility." (PMID 35282834, 2022). "We aimed to dissect SULT1A1 modulation of CSD susceptibility and behavior in an in vivo experimental model using hesperidin, a SULT1A1 inhibitor found in citrus fruits (known migraine triggers) and mefenamic acid (SULT1A1 inhibitor), an NSAID to simulate medication overuse." (PMID 35282834, 2022). "Therefore, we aimed to dissect SULT1A1 modulation of CSD susceptibility and behavior in an in vivo experimental model using hesperidin, a SULT1A1 inhibitor found in citrus fruits (known migraine triggers) and mefenamic acid (SULT1A1 inhibitor), an NSAID to simulate medication overuse." (PMID 35282834, 2022). "Non-steroidal anti-inflammatory drugs (NSAIDs) used in acute migraine attacks such as mefenamic acid, diflunisal, nimesulide, diclofenac, salicylic acid, ketoprofen, indomethacin, ibuprofen, ketorolac and naproxen have also been shown to inhibit SULT1A1 enzymes." (PMID 35282834, 2022). "Hesperidin was used as SULT1A1 inhibitor found in citrus fruits, known migraine triggers and mefenamic acid (NSAID), another SULT1A1 inhibitor, was used to induce MO in rats." (PMID 35282834, 2022). "SULT1A1 values were shown to be lower in dietary migraine subjects compared to non-dietary migraine group and healthy controls." (PMID 35282834, 2022).
steatosis (2 papers, 2022 to 2024). Increased lipid within the cytoplasm of cells. "SULT1A1 activity is significantly increased in patients with steatosis but decreased in those with NASH, leading to disruptions in the sulfonation of acetaminophen during NAFLD progression." (PMID 39720713, 2024).
acute kidney injury (1 paper, 2021). Sudden and sustained deterioration of the kidney function characterized by decreased glomerular filtration rate, increased serum creatinine or oliguria. "Here, we demonstrate the toxico-pathological roles of indoxyl sulfate (IS), a sulfate-conjugated uremic toxin, and sulfotransferase 1A1 (SULT1A1), an enzyme involved in its synthesis, in cisplatin-induced acute kidney injury using Sult1a1-deficient (Sult1a1-/- KO) mice." (PMID 33578912, 2021).
acute leukemia (1 paper, 2015). A clonal (malignant) hematopoietic disorder with an acute onset, affecting the bone marrow and the peripheral blood. "An association of SULT1A1 (c.638G>A) in males and acute leukemia was found." (PMID 25992585, 2015). "Genotype frequencies of CYP1B1, CYP3A5, GSTT1, GSTM1 and SULT1A1 in females and early age acute leukemia, Brazil, 2000–2012." (PMID 25992585, 2015). "Genotype frequencies of CYP1B1, CYP3A5, GSTT1, GSTM1 and SULT1A1 in males and early age acute leukemia, Brazil, 2000–2012." (PMID 25992585, 2015).
AIDS (1 paper, 2016). A syndrome resulting from the acquired deficiency of cellular immunity caused by the human immunodeficiency virus (HIV). "Consequently, we are now seeking to determine if there is a correlation between SULT1A1 variability and HIV-1 susceptibility and/or AIDS disease progression." (PMID 26906565, 2016).
allergic rhinitis (1 paper, 2024). Inflammation of the nasal mucous membranes caused by an IgE-mediated response to external allergens. "Miscellaneous diseases and traits that were associated with SULT1A1 were risk-taking tendency, allergic rhinitis, alcohol frequency, red blood cell count, tonsillectomy, and mosquito bite size." (PMID 39457450, 2024).
anemia (1 paper, 2023). A reduction in the number of red blood cells, the amount of hemoglobin, and/or the volume of packed red blood cells. "Therapy targeting Sult1a1 may demonstrate the ability to treat UUO-related anemia." (PMID 37511089, 2023).
asthma (1 paper, 2009). "Our SAGE data demonstrated that Sult1a1 was up-regulated in asthma, which indicated the gene may catalyze the sulfation process of steroidgensis." (PMID 19419550, 2009). "The genes involved in the classification were: MGP, Abca2, and Sult1a1, which demonstrated that the transportation and production of steroid hormone may be regulated by acupuncture in the EAR phase of asthma at the level of transcription." (PMID 19419550, 2009).
cholesteatoma (1 paper, 2014). A pathologic process characterized by the proliferation of keratinizing squamous epithelium resulting in the accumulation of keratin and cells in the middle ear and/or mastoid. "In the present study, around 30–40 fold higher levels of STS were found in cholesteatoma compared to the tympanic membrane and EACS, whereas a counter-acting enzyme Sulfotransferase 1A1 (SULT1A1) was down-regulated to the same degree, perhaps indicating activation and a resulting over-desquamation." (PMID 25093596, 2014).
chronic lymphocytic leukemia (1 paper, 2017). "A Western blot analysis revealed that SULT1A1 was expressed in the AML samples but not in the chronic lymphocytic leukemia sample that was testable (sample 3; sample 4 was too small for Western blotting)." (PMID 29254232, 2017).
Constipation (1 paper, 2025). Infrequent or difficult evacuation of feces. "We found that the expression level of SULT1A1 in postbiotic of hawthorn-probiotic (FS) was lower than that in constipation model (M)." (PMID 40070478, 2025).
coronary artery disease (1 paper, 2012). "The marker SNP rs8028182 was found to be associated with sudden cardiac arrest in patients with coronary artery disease; SULT1A1, an experimentally validated target of miR-631, has been associated with the risk factor of coronary artery disease." (PMID 23049969, 2012).
genitourinary cancers (1 paper, 2008). "The SULT1A1*2 revealed contrasting risk association for UADT cancers (OR=1.62, 95% CI: 1.12, 2.34) and genitourinary cancers (OR=0.73, 95% CI: 0.58, 0.92)." (PMID 18854828, 2008).